IL6 (interleukin 6)
Diseases named in the same sentence as IL6 in open-access papers (continued):
Sharing a sentence is not in itself a finding about the gene and the disease.
infection (continued). "The initial inflammatory response during infection usually leads to the release of proinflammatory mediators like TNF-α, IL-1, IL-6, and NO by classically activated macrophages, and these have been shown to play important roles in mediating early protection during infection." (PMID 31824512, 2019). "In this study, we did not observe any significant increased IL-6 expression in any koala to natural infection, at pre-vaccination." (PMID 30615687, 2019). "Although GM-CSF, IL6 and IL12p35 were significantly up regulated after 12 h of infection, they were not up regulated after 24 h of infection, and additionally, TNF-α was not significantly expressed in IPAMs." (PMID 30918280, 2019). "In contrast, the expression levels of TNF-α (P = 0.039), IL-22 (P = 0.033) and IL-6 (P = 0.016) in jejunal mucosa at 12 h and IL-22 (P = 0.030) expression in ileal mucosa at 72 h post infection, were markedly upregulated in nonspecific yolk powder group." (PMID 31286936, 2019). "Amongst cytokines, the genes for Cxcl9, Cxcl10, Cxcl13, Il-1β, Il-6, Tnf, Tnfsf10, IFN-γ, Ccl2, Ccl4, Ccl7, Ccl17, and Mif were highly up-regulated (ranging from 2- to 405-fold, p ≤ 0.05), whereas Cxcl12 and Cxcl14 were down-regulated during in vivo infection." (PMID 30857242, 2019). "The infection results showed that EDL933(ΔTir + Y490F) and EDL933(ΔTir + Y519F) induced much higher production of Tnf, Il6 and Il12b than the EDL933(ΔTir + HA-Tir) strain in mouse primary peritoneal macrophages, and EDL933(ΔTir + Y490F, Y519F) induced even higher cytokine production." (PMID 31130074, 2019). "Patients with prolonged arthralgia during MAYV infection show that levels of IL-1Ra, IL-6, IL-7, IL-8, IL-13, IL-17, G-CSF, IFN-γ, PDGF- α, VEGF and IL-12p70 remained elevated up to 12 months after infection." (PMID 31050676, 2019). "Our previous studies demonstrated that LPS infection could activate the MAPK signaling pathway, and induce IL-6 and TNF-α overproduction." (PMID 30909903, 2019). "According to this, experiments in the A549 cell line (human alveolar type II-like epithelial) with the Long strain of hRSV showed that infection with hRSV induces the secretion of IL-6, CCL3, and CCL5 at 48 h post-infection as compared to non-infected cells." (PMID 30936869, 2019). "In contrast, IL-6 is regarded as a nonspecific inflammatory marker and has low specificity for infection, and our results are in accordance with these previous findings." (PMID 31261907, 2019). "After 6 h of infection, the production of IL-6, CXCL1, and CCL2 increased in WT PMCs, but not in Tlr2-deficient PMCs (P < 0.001, for each at MOIs of 0.05 and 0.1)." (PMID 31636643, 2019). "At 1 week after infection, several cytokines responsible for immune cell recruitment were significantly up-regulated in infected-only control defects, including G-CSF, MIP-1α, MIP-1β, MIP-2, KC, IP-10, IL-6, and IL-1β." (PMID 31114804, 2019). "Besides, serum levels for MCP-1, TNF-α, and IL-6 were increased already 3 h pi with S. aureus compared to PBS-treated mice followed by IL-12 and IFN-γ 6 h pi, indicating an infection-induced proinflammatory response." (PMID 31134074, 2019). "Infection triggered similar cytokine storms in both genotypes as illustrated by the equivalent large quantities found in the bloodstream of Ripk1LPC-KO and Ripk1fl/fl mice, such as for TNF-α, IL-6, and CCL2." (PMID 30622241, 2019). "In addition to de novo expression of a number of immunological important cell surface molecules, including CD200, CD11a, CD11b, microglia produce several cytokines and chemokines such as IL-6, IL-10, TNF, and GM-CSF in TE and upon infection in vitro." (PMID 30873157, 2019). "However, the moderate infection invoked a stronger response from the immune system, as indicated by the higher levels of pro-inflammatory mediators (TNF and IL-6) compared to the mild case." (PMID 31681022, 2019).
infection (continued). "IL-1β, TNFα, IL-6 and IFNγ were not significantly elevated during relapses compared to pre-infection values, and Monokine Induced by Interferon Gamma (MIG) was the only cytokine significantly increased during relapses." (PMID 31536608, 2019). "All serologic tests showed poor prognostic value in predicting persisting infection, with the AUC of 61.6% (95% CI, 42.2 to 80.2%) for CRP, 57.8% (95% CI, 37.2 to 78.8%) for ESR, 60.3% (95% CI, 43.5 to 73.3%) for IL-6, and 62.1% (42.4 to 81.0%) for the combination of the three tests." (PMID 31159792, 2019). "Although numerous serological markers for PJI have been evaluated in the past, including interleukin 6 (IL-6), erythrocyte sedimentation rate (ESR) and C-reactive protein (CRP) have been generally used as a screening test for infection because of their simplicity and cost-effectiveness." (PMID 31358018, 2019). "Furthermore, NLRP3 inflammasome inhibition was found to decrease IL-6 and IFN-γ levels in BAL from BALB/c mice but only IFN-γ levels in the case of C57BL/6 mice on day 5 post-infection." (PMID 30964929, 2019). "Albeit not statistically significant, the levels of G-CSF, IL-1α, MCP-1/CCL2, MIP-2/CXCL2 at day 1, G-CSF, KC, MCP-1, and MIP-2 at day 2, and IL-1α, IL-1β, IL-6, IL-10, MCP-1, MIP-2, and TNF at day 3 post-infection were 1.5–4.4-fold higher in SIRT3/5−/− than in SIRT3/5+/+ mice." (PMID 31632409, 2019). "Hpb-infected mice demonstrated marked increase of helminth antigen-specific IgG1, IgA and IgE but not IgG2a antibody responses after 9 weeks of infection, concomitant with an increase of systemic IL-10 and IL-6 levels." (PMID 30685251, 2019). "Dectin-1-induced IL-6 and IL-6-mediated antibody responses were increased during infection with C. albicans in the absence of CD37 resulting in increased pathogen clearance." (PMID 29522806, 2019). "Maternal infection was associated with a 7% lower CRP level (95% CI, − 17,5%) among offspring compared with offspring born to women without an infection and similarly an 8% lower level of IL-6 (95% CI -15,1%), and a 9% lower level of IL-10 (95% CI, − 23,20%)." (PMID 30923624, 2019). "The STAT3 targets that increased in the early infection were mainly inflammatory regulators including pro-inflammatory factors IL1B, IL6 and immunosuppressive factor IL10, which might contribute to the immune regulatory role of glia in CNS during infection." (PMID 31575039, 2019). "Here, restriction of dietary Zn intake resulted in only an increase in the activation of IL-1β and IL-6, but without infection resulting in a generalised dysregulation of inflammatory responses." (PMID 31437249, 2019). "In the CNS of WT mice, increased IFN-α1, IFN-β, TNF, IL-1α, IL-1β, IL-6, and IFN-γ mRNA levels were seen at day 4 post infection, and with the exception of IFN-α1, which decreased slightly, cytokine mRNA levels increased further by day 6 post infection." (PMID 31511023, 2019). "Indeed, HRV-infection of BE co-cultured with asthmatic BSM increased the production of pro-inflammatory mediators (IL-1A, IL-6, TNF-alpha) at the transcriptional level compared to that co-cultured with control BSM cells." (PMID 31969885, 2019). "Upon infection, SIS models produced much more IL-6 in comparison to Transwell® models." (PMID 31417529, 2019). "Relative to untreated controls (infected with HIV and M. tuberculosis), GaTN and GaM decreased IL-6 and IL-8 by 40-fold and 70-fold, respectively, regardless of number of days after drug loading prior to infection." (PMID 31341073, 2019). "Furthermore, infection with VSV in PINK1 knockout macrophages showed similar statistically significant decreases in IFN-β and IL-6 expression." (PMID 31139191, 2019). "In the absence of infection, senescent cells show increased, low-grade, basal systemic inflammation (characterized by higher levels of IL-1β, IL-6, and tumor necrosis factor-α), which is known as inflammaging." (PMID 30940096, 2019).
infection (continued). "Similarly, treatment of bMDM with IL10 siRNA enhanced expression of IL1B, TNF, IL6, IFNG and NOS2 induced by G18 infection." (PMID 31527895, 2019). "In accordance with the attenuated cytokine response in vivo, IL-6 responses in the ex vivo whole blood infection model showed a (non-significant) down-trend for all ATR-knockout mice compared to WT." (PMID 31274379, 2019). "In addition, the levels of pro-inflammatory cytokines (IL-2, IL-6, IL-12, TNF-α, IFN-α, IFN-γ) were higher in il10−/− mice than in wild-type mice at 1, 3, and 6 h post infection." (PMID 31551984, 2019). "Early after infection, TNFα, IL6 and IL12p40, but not IL1β, remained present at significantly higher levels in BAL cell supernatants from cynomolgus macaques." (PMID 31736945, 2019). "A substantial decrease in IL-6, IL-9, IL-12p40/p70, IL-13, IL-17, IFN-γ, CCL5, SCF, TNF-α, TPO, and vascular endothelial growth factor (VEGF) was observed across days 4 through 7 of NTHi infection." (PMID 31548315, 2019). "Pro-inflammatory cytokines (IL-6, TNF-α, IL-12, IFN-γ, and the chemokine CCL2/MCP-1) were up-regulated in plasma of morphine-treated mice collected 8 h after infection, which was interpreted to be the result of the increased systemic bacterial burdens with the pathogen in animals given morphine." (PMID 31921165, 2019). "Despite this, cytochalasin did not reduce MDM supernatant TNF, IL-6, and IL-1β (not shown) responses to infection with either the TIGR4 or the TIGR4 Δcps strain, with most responses actually showing non-statistically significant increases." (PMID 31551336, 2019). "P. protogens was not significantly invasive in vitro and elicited a minimal IL-6 response following infection." (PMID 30606251, 2019). "Induction of IL-6 was observed in SBCMV infected cell supernatants at 24 h after infection, but the induction of TNF-α was absent." (PMID 30909422, 2019). "Many of these proinflammatory mediators, including IL-6, MCP-1, TNFα, IFNγ, RANTES and IL-1β, were also present at high concentrations on days 4 and 6 of infection in the spleen, a major target tissue for SFTSV replication and pathology, as well as other tissues." (PMID 31546590, 2019). "Thus, Mφ were required in order to observe a predominant secretion of IL-6 and TNF-α in response to PA, PB and ST infection, and CCL3 in response to PA." (PMID 31412039, 2019). "In contrast to the effect of IL10 knock-down during G18 infection of bMDM, IL1B and IL6 mRNA levels were not significantly affected by IL10 knock-down during AF2122/97 infection." (PMID 31527895, 2019). "At the same time, indicators of inflammatory response such as production of IFN-γ, TNF-α, IL-1β, and IL-6 mediated by TLR/MyD88/NFκB were also activated after N67 infection, which may explain the pathology and host death later in infection." (PMID 30327482, 2018). "Regarding inflammation, infection of MT increased TNF-α, IL-6 and IL-8 expression." (PMID 30297793, 2018). "Based on these findings we hypothesize that the activated microglia in μBS play a potential role in enhancing the expression of pro-inflammatory cytokines such as interleukin (IL)-1β, IL-6, and TNF-α in response to ZIKV-BR infection." (PMID 30619100, 2018). "“Sterile” chronic, low-grade inflammation without any obvious infection is a common feature of ageing, and people over the age of 65 have increased serum levels of IL-6, TNF, and IL-1855,56." (PMID 29426925, 2018). "However, when exogenous stimulation is applied via LPS even 8 days after infection with HBV, KC rapidly secrete IL-6 and TNF-α." (PMID 29445209, 2018). "In immature MDDCs, while the measured concentration was less than the control cells in many cases, the concentrations of a number of cytokines/chemokines (IL-6, IP-10, MIP-1α, MCP-1) increased over the course of the infection, specifically on days 6 and 8 when titers were highest." (PMID 29566060, 2018).
infection (continued). "In comparison, the expression of IL-1β, TNF-α, and IL-6 is not markedly changed 12 h after infection, which is markedly increased 24 h and 48 h after infection." (PMID 30186539, 2018). "According to findings of a study by Ganz, infection and inflammation increase the level of interleukin-6 in the body, independent of serum iron levels." (PMID 31239849, 2018). "Although LPC treatment increased production of the pro-inflammatory cytokines TNF-α and IL-6 in a dose-dependent manner in Mtb-infected macrophages (data not shown), the production of TNF-α and IL-6 was decreased in LPC-treated WT BMDMs after H37Ra infection." (PMID 29755479, 2018). "IL-6, IL-10 and G-CSF showed smaller, non-significant elevations in R. felis mono-infection when compared to healthy controls." (PMID 29736763, 2018). "Our findings suggest that CagA and the CagA translocation process per se are not required for IL-8 or IL-6 induction by H. pylori during infection of endothelial cells." (PMID 29468142, 2018). "Previous studies have demonstrated that, during infection of immortalized epithelial cells, GAS activates the AP-1, NF-κB, and MAPK pathways, leading to increased expression and secretion of key cytokines and chemokines, particularly IL-8 and IL-6." (PMID 29868516, 2018). "MG groups had higher levels of TNF-α, IL-1B, and IL-6 compared to no-infection groups (both miR-451-M and miR-451-Inh), as a result of the higher gga-miR-451 expression in the MG group." (PMID 29652844, 2018). "Consequently, the level of ROS and inflammatory cytokines, including IL-6 and TNFα, elevated during PAO1 infection, and their production altered as a result of the genetic manipulation of gp91phox and NF-κB p65, as well as NAC treatment." (PMID 30050663, 2018). "We also observed reduced IL-6 expression in IFNAR KO BMDMs at 36 h after infection and enhanced IL-1β secretion in BMDCs lacking IFNAR." (PMID 30233599, 2018). "A network of molecules intersects with these antioxidant proteins, including NF-kB, IL6, COX-2, iNOS, Nrf2, and small molecules, suggesting multiple points at which MHV-68 infection might generate an oxidative stress in the lungs." (PMID 30486363, 2018). "Neither DENV-2 nor DENV-3 stimulation resulted in substantial up-regulation of IL-6 production, although DENV-3-stimulated wells showed a non-significant trend toward higher levels of IL-6 in subjects with symptomatic infection (p = 0.061)." (PMID 30557313, 2018). "Similar to airway epithelial cells, human macrophages express type I and type III IFNs, IL-1α, IL-1β, IL-6, TNF-α, CXCL8, CCL2 (MCP-1), CCL3 (MIP-1α), CCL4 (MIP1-β), CXCL9, and CXCL10 following infection with seasonal H1N1 or with H5N1, 2009 H1N1 strains demonstrating increased pathogenicity." (PMID 29623073, 2018). "Expression of viral RNA, as well as Ccl5 and Cxcl10, but not Tnfα, Il6 Ccl2, Ifna and Ifnb, was significantly decreased in the footpads of Bclx+/- mice at 5 days post-infection." (PMID 30261081, 2018). "We do not recommend the routine measurement of IL-6 levels as an adjunct to the diagnosis of infection in such patients (2C) (rate of agreement, 89.4%)." (PMID 29435330, 2018). "Both IL-6-treated or untreated LNCaP-JAK1 cells displayed similar high levels of GFP expression upon HIV-GFP infection, implying that IL-6 treatment did not perturb viability and function of infected cells." (PMID 29441069, 2018). "IFN-γ and IL-6 levels were higher in some Rag1−/− mice that received peritoneal B cells than mice that did not 14 d post-infection." (PMID 28837391, 2018). "For EHDV-TAU, IL-6 induced oncolysis in the absence of productive infection, while this cytokine augmented the mild cytolytic activity of hMPV-GFP." (PMID 29441069, 2018). "During infection, MG interacts with host respiratory epithelial cells and generates an inflammatory response, resulting in increased levels of cytokines, such as tumor necrosis factor alpha (TNF-α), interleukin-6 (IL-6), and interleukin-2 (IL-2)." (PMID 29652844, 2018).
infection (continued). "To confirm that cells of haematopoetic origin contribute to the excessive IFN-α in vivo in 6:2 Tky/05 virus infected mice, we FACS purified CD45-positive cells from lungs harvested 2 days post infection and performed qRT-PCR for viral RNAs and for IFN-α and IL-6 mRNAs." (PMID 29300777, 2018). "It is important to emphasize that we evaluated individuals with no infection at the moment of sample collection; therefore, we evaluated the basal levels of IL-6." (PMID 30186038, 2018). "Interleukin 6 (IL-6) is a classic proinflammatory cytokine that signals through STAT3 as part of the acute phase response (APR), a nonspecific reaction of the innate immune system to pathogen infection." (PMID 29543893, 2018). "We report a strong induction of numerous pro-inflammatory cytokines, chemokines and AMPs such as CXCL1, CXCL2, CXCL5, CXCL8, CCL20, TNFα, TSLP, IL-23α, IL-32, IL-6, hBD2 and S100A7 during the infection of monolayered primary keratinocytes and reconstructed epidermis with the wild-type PAK strain." (PMID 30070169, 2018). "In the MIF-/- group, the increase in IL-6 secretion, due to infection, was detected only in the non-pregnant mice (P < 0.01)." (PMID 29867817, 2018). "Infection with the ΔgliP mutant significantly stimulated the expression of CXCL2, CCL3, CCL4, CCL7, TNF-α, and IL-6, whereas infection with the Δaspf1 ΔgliP double mutant significantly decreased the expression of CXCL2, CCL7, TNF-α, and IL-6." (PMID 30052103, 2018). "In infected MIF-/- females, infection induced IL-6 upregulation only in non-pregnant females (P < 0.05)." (PMID 29867817, 2018). "Significant differences in biomarkers (higher Hp and IgG1; lower SAA and IL-6) between perinatal mortalities and live perinates probably reflect differences between these two groups in age at sampling (SAA and IL-6) and in utero infection (IgG1)." (PMID 30382887, 2018). "Knockout mice lacking functional IL-4 also experienced a more severe infection than wild type mice; wild type mice, unlike the knockout mice, were able to up-regulate several cytokines, including IL-6, IL-10, and MIP-2." (PMID 29320451, 2018). "We note that TNFα, IL-6 and IL-10 are induced also by HSV, so their presence may in part be consequent to infection." (PMID 30080893, 2018). "This indicates that Th2 stimulation by macrophage-derived IL-6 does not play a major role in this infection mode." (PMID 30081942, 2018). "Compared to those of mock infection or VR2332c, JA142c and poly I:C induced significantly increased transcript levels of IFN-β and pro-inflammatory cytokines (IL-1α, IL-1β, IL-6, IL-8, IL-12, and TNF-α) at either two or all three time points assayed (12, 24 and 36 hpi)." (PMID 30509265, 2018). "Minimum adequate models (MAMs) for effects of infection with Mycoplasma gallisepticum isolates VA1994 and NC2006 on house finch expression of cytokines IL1B, IL6, IL10, CXCLi2, and TNFSF15 in internal eyelid (nictitating membrane) across three different time points." (PMID 29403495, 2018). "This indicates that the IL-6-induced restriction to hMPV infection can be attributed to caspase-mediated cell death, while this cytokine induces a cell state which is intrinsically refractory to EHDV-TAU infection, independently of the induction of cell death." (PMID 29441069, 2018). "The results indicated that IL-6, IL-10, TNF-α, TGF-β, and iNOS expression in the infection group was significantly higher than in the control group, an increase of 1.2-fold, 0.29-fold, 0.32-fold, 0.12-fold, and 3.95-fold, respectively, as well as an increase of CD86 (P = .891) and CD206 (P = .303)." (PMID 30170447, 2018). "At 2–6 h post infection, S. epidermidis nosocomial strain 1457 was demonstrated to induce a rapid production of cytokines, such as TNF-α, IL-1β, IL-6, IL-12p70 and IL-10, as well as chemoattractant protein-1 (MCP-1), granulocyte-colony stimulating factor (G-CSF), CCL2 and CXCL1." (PMID 29405832, 2018).